IL6 (interleukin 6)
Diseases named in the same sentence as IL6 in open-access papers (continued):
Sharing a sentence is not in itself a finding about the gene and the disease.
atherosclerosis (continued). "Biomarkers such as TNF-α, IL-6, and leukotrienes could be used for real-time tracking of atherosclerosis progression, allowing for earlier intervention before clinical symptoms arise." (PMID 40217801, 2025). "This review explores the intricate interplay between inflammatory mediators—such as tumor necrosis factor-alpha (TNF-α), interleukin-6 (IL-6), and interleukin-17 (IL-17),—adipokine imbalances, and lipid metabolism abnormalities, all of which foster endothelial dysfunction and atherosclerosis." (PMID 40137170, 2025). "In an animal atherosclerosis model, aged mice, compared to young mice, showed a higher progression of atherosclerosis due to hyperlipidemia-exacerbated mitochondrial dysfunction elevating Parkin and IL-6." (PMID 40277943, 2025). "Peel extract down-regulates IL-6 and adhesion factors, reduces the adherence of monocytes and endothelial cells, decreases the monocyte/macrophage content within the plaque, and alleviates atherosclerosis." (PMID 41515139, 2025). "The chronic inflammatory environment present in atherosclerosis, marked by elevated cytokines such as IL-1β, IL-6, TNF-α, and interferon-gamma (IFN-γ), promotes oxidative stress and DNA damage in HSCs, particularly given their high turnover rates required to sustain lifelong hematopoiesis." (PMID 41516113, 2025). "Furthermore, radiation increases many inflammatory markers such as tumor necrosis factor, interleukin-6, platelet-derived growth factor, and transforming growth factor, leading to atherosclerosis formation." (PMID 40283126, 2025). "IL-6 has been identified as a key mediator of atherosclerosis and CVD." (PMID 40265387, 2025). "To evaluate the effect of sodium nitrate on atherosclerosis, we detected inflammatory cytokine expression in mouse aortas by using QPCR and found that the expression levels of IL-1β, IL-6, IL-8, and TNF-α, especially IL-8, were significantly decreased in the sodium nitrate treatment group." (PMID 40110129, 2025). "Keywords such as “intradialytic parenteral nutrition”, “atherosclerosis”, “interleukin-6”, and “amino acids” were prominent during this period, reflecting an emphasis on understanding the immediate nutritional and inflammatory consequences of renal failure and its treatment." (PMID 41516959, 2025). "Most of the proposed interventions are expected to cause direct or indirect inhibition of the nucleotide‐binding domain leucine‐rich repeat and pyrin domain containing receptor 3 (NLRP3)‐IL‐1β/‐IL‐6 axis, because there is strong evidence for its involvement in atherosclerosis." (PMID 41182006, 2025). "Additionally, studies have found that people with an eGFRcys/eGFRcr ratio <0.6 have higher levels of proteins related to atherosclerosis and cell proliferation, such as IL-6, CXCL10 and FGF23." (PMID 40235956, 2025). "In addition, IH causes systemic inflammation that is marked by increased cytokine levels, including tumor necrosis factor-alpha (TNF-α) and interleukin-6 (IL-6), which worsens endothelial function and accelerates atherosclerosis." (PMID 41426756, 2025). "Interleukin-6 (IL-6) is a pro-inflammatory cytokine that plays an important role in the immune response and is considered an important inflammatory marker in the process of atherosclerosis." (PMID 40362309, 2025). "It remains to be proven whether the reductions in CRP or IL-6 achieved with probiotics will translate into fewer cardiac events or slower atherosclerosis progression." (PMID 41156763, 2025). "The study results showed that ziltivekimab significantly reduced levels of biomarkers of atherosclerosis-related inflammation and thrombosis, such as hsCRP, compared with placebo, which further demonstrated the important role of IL-6 in atherosclerosis and thrombosis." (PMID 39982801, 2025). "Thus, combining IL-6 inhibitors with ICB holds promise for improving cancer immunotherapy while reducing the risk of adverse events, including atherosclerosis." (PMID 39796190, 2025).
atherosclerosis (continued). "Additionally, impaired triglyceride metabolism stimulates the secretion of pro-inflammatory cytokines, such as TNF-α, IL-6, and IL-1β, leading to systemic inflammation and endothelial dysfunction—both of which accelerate the progression of atherosclerosis." (PMID 40077648, 2025). "In addition to the key role in the initiation and progression of tumors, IL-6 is also a typical cytokine involved in systemic inflammatory responses in the body and participates in the process of atherosclerosis." (PMID 40251177, 2025). "In addition, chronic low-grade inflammation, particularly involving IL-6, interleukin 8 (IL-8), and TNF-α, is considered to be associated with the pathogenesis of hypertension and atherosclerosis." (PMID 40034990, 2025). "Previous studies have indicated that aging may accelerate atherosclerosis through the synergistic effects of IL-6 signaling, decreased vascular mitochondrial function, and impaired mitochondrial autophagy." (PMID 40255889, 2025). "Nevertheless, CANTOS catalysed a paradigm shift, reinforcing inflammation as a modifiable driver of atherosclerosis and stimulating subsequent investigations of alternative agents with more favourable safety profiles, such as low-dose colchicine and IL-6 pathway inhibitors." (PMID 41515595, 2025). "The study of one single cytokine role in atherosclerosis is extremely difficult, seeing that some of these biomarkers induce the activity of others; for example, IL-1 induces IL-6, IL-18, and CRP, for which a combination of cytokines is possibly a better choice." (PMID 41226718, 2025). "IL-6 is an upstream inflammatory mediator in atherosclerosis." (PMID 40600192, 2025). "CRP and IL-6 contribute to both atherosclerosis and kidney damage." (PMID 40376312, 2025). "Given the dual nature of IL-6 in the development of atherosclerosis, it makessense to study other IL-6 signaling mediators as targets, which determine whetherthe IL-6 signal will go via the classical or trans-pathway." (PMID 40160593, 2025). "Persistent low-grade inflammation, characterized by moderate increases in circulating pro-inflammatory cytokines (C-reactive protein: CRP; interleukins (IL): IL-6, IL-2, IL-7, IL-8, etc.), plays a significant role in all atherosclerosis formation and progression phases." (PMID 40428891, 2025). "Additionally, systemic inflammation in asthma, driven by cytokines like IL-6, IL-13 and TNF-α, has been linked to endothelial dysfunction and vascular damage, key processes in atherosclerosis." (PMID 40332077, 2025). "Moreover, using RSV 50 μM in cultured cortical cells improves atherosclerosis disease by blocking IL-6 gene expression and, in turn, IL-6 synthesis; IL-6 is a circulating cytokine recognized as another inflammatory marker found in atherosclerotic plaques." (PMID 41228388, 2025). "Prior studies indicate that celastrol significantly reduces inflammation by inhibiting pro-inflammatory cytokines, such as IL-6, while also mitigating the harmful effects of oxidized low-density lipoprotein (oxLDL), both of which are crucial in the pathogenesis of atherosclerosis." (PMID 40362727, 2025). "Proinflammatory cytokines, such as tumor necrosis factor-alpha (TNF-α) and interleukin-6 (IL-6), play a pivotal role in the progression of both RA and atherosclerosis, creating a shared pathological pathway that exacerbates cardiovascular risks in these patients." (PMID 40552192, 2025). "Studies have also demonstrated that high concentrations of proinflammatory molecules, including tumor necrosis factor-alpha (TNF-α) and interleukin-6 (IL-6), contribute to the accelerated development of atherosclerosis and cardiovascular events in patients with RA and SLE." (PMID 40046046, 2025). "CHD is closely linked to atherosclerosis, which is a chronic inflammatory condition characterized by the involvement of inflammatory mediators such as high-sensitivity C-reactive protein (hs-CRP), interleukin-6 (IL-6), and tumor necrosis factor-alpha (TNF-α)." (PMID 39953634, 2025).
atherosclerosis (continued). "As VEGF, CRP, IL-6 and TNF-R1 are regarded as biomarkers for atherosclerosis this implies that patients in the RA risk group might already have a higher cardiovascular disease risk." (PMID 39012360, 2024). "Cytokines and growth factors initiate the JAK/STAT pathway, and the downstream of JAK/STAT includes diverse genes involved in proliferation and apoptosis in atherosclerosis, such as IL-6, interferon (IFN)-γ, TNF-α and the suppressor of cytokine signaling (SOCS)." (PMID 39598338, 2024). "Patients with atherosclerosis also had higher levels of IL-6 in the blood than patients without atherosclerosis, and patients with unstable angina showed higher levels of circulating IL-6 than patients with stable angina." (PMID 38256155, 2024). "In addition, there are already some biomarkers for atherosclerosis, such as serum interleukin-1β, interleukin-6, and homocysteine levels, and the mechanisms of the effect of JMJD6 and other biomarkers of inflammation differ." (PMID 38732153, 2024). "Additionally, a study on subclinical atherosclerosis demonstrated an independent positive correlation between glutamate and IL-6 levels." (PMID 38360971, 2024). "In the context of CAD patients, elevated blood levels of IL‐6 may play a crucial role in the transformation of macrophages into foam cells during the atherosclerosis process." (PMID 39669190, 2024). "Evidence has demonstrated that larger or younger platelets might cause prominent adverse effects such as inflammation response and atherosclerosis by elevating the secretion of inflammatory cytokines (such as IL-6 and CRP) compared to older platelets." (PMID 39195631, 2024). "If we had also analyzed the levels of some cytokines such as IL-1 or IL-6, which are involved in the NF-κB pathway, we could have better evaluated the correlations of endocan with inflammatory cytokines involved in atherosclerosis." (PMID 39230149, 2024). "Therefore, this study aimed to gain insight into the relationship between plasma concentrations of TNF, VEGF, IL-6, and radiological parameters of atherosclerosis progression in patients with early-onset coronary artery disease (CAD)." (PMID 38541966, 2024). "IL-6 induced EREG in coronary artery smooth muscle cells to induce atherosclerosis." (PMID 38276286, 2024). "IL-6 is a unique pleiotropic cytokine, which may play a role in promoting and anti-atherosclerosis in the formation and progression of atherosclerosis." (PMID 39496055, 2024). "However, thus far only agents targeting the IL-1β—IL-6 pathway have shown some efficacy in atherosclerosis." (PMID 38993522, 2024). "Vascular inflammation is known to cause atherosclerosis, so we investigated the impact of GV1001 on the development of vascular inflammation by determining the levels of the major proinflammatory cytokines, such as IL-1β, TNF-α, and IL-6." (PMID 38892314, 2024). "Soluble mediators IL-6, TNF-α, and D-dimer are associated with chronic HIV infection as well as various drivers of atherosclerosis including endothelial dysfunction, increased carotid intima-media thickness (cIMT), and transmigration of inflammatory subsets of monocytes." (PMID 39000373, 2024). "Additionally, increased concentrations of interleukin-1 and interleukin-6, key pro-inflammatory cytokines, correlate with endothelial impairment and the development of atherosclerosis." (PMID 39469331, 2024). "Since serum IL‐6 levels were primarily determined by rs180079517, 18 and were closely linked to CAD3, 4, 5 and atherosclerosis, it is tempting to speculate that rs1800795 may influence the risk of CAD and atherosclerosis by modulating serum IL‐6 levels." (PMID 38634217, 2024). "Furthermore, high serum levels of IL-6 correlate with endothelial dysfunction, arterial stiffness, and atherosclerosis severity." (PMID 39273602, 2024).
atherosclerosis (continued). "IL-6 levels are elevated in adipose tissue of diabetic and obese patients, especially those with MetS characteristics, and elevated IL-6 concentrations have been reported to be related to hypertension, atherosclerosis, and cardiovascular events." (PMID 39139641, 2024). "Notably, inflammatory mediators like TNF-α and IL-6 impair nitric oxide production and endothelial function, contributing to atherosclerosis and CVD development." (PMID 39337647, 2024). "Thus, IL-6-related oxidative stress of atherosclerosis counterbalances the antiatherosclerosis effect of GLP-1RA, leading to an aHR of CAD and heart failure with a null effect." (PMID 38540106, 2024). "These cytokines affect lipid uptake and metabolism by promoting the proliferation of vascular endothelial cells and smooth muscle cells, leading to the formation of atherosclerosis and the production of large amounts of IL-6 and IL-8 involved in the stress response." (PMID 38836066, 2024). "Thus, in atherosclerosis, baseline IL-6 levels have regulatory effects on lipid homeostasis, vascular remodeling, and plaque inflammation." (PMID 38799170, 2024). "IL-6 is an effector cytokine downstream of IL-1β, playing a significant role in atherosclerosis." (PMID 38993522, 2024). "Analogous tactics may be employed for additional pro-inflammatory cytokines, like IL-6 and TNF-α, which are also implicated in intensifying the inflammatory cascade in atherosclerosis." (PMID 39712846, 2024). "In addition, some main circulating biomarkers in metabolic syndrome were not present in 22 inflammatory proteins in our study, such as IL6, which is linked to low HDL-C and high TGs, impairment of glucose metabolism, vascular dysfunction, and atherosclerosis." (PMID 38649851, 2024). "The link between periodontal disease and atherosclerosis may be related to the effect of bacteria on the blood vessels, where they can initiate inflammation involving pro-inflammatory cytokines, including IL-6." (PMID 38396821, 2024). "These two regions may serve as major players in immunological and inflammatory pathways, while it is known that IL6 is a key cytokine involved in RA pathogenesis and the RA–atherosclerosis relationship." (PMID 38892172, 2024). "For example, mRNA vaccines might be created to inhibit the synthesis of IL-1β or IL-6, two cytokines that are essential for both systemic and local inflammation in atherosclerosis." (PMID 39712846, 2024). "CD86, a biomarker of M1-type macrophages, is markedly expressed in vulnerable arterial plaques.M1-type macrophages release ROS and pro-inflammatory cytokines, such as TNF-α, IL-1β, IL-6, and IL-12, which damage endothelial cells and blood vessels and promote atherosclerosis." (PMID 38382092, 2024). "Combined with TNF-α levels, IL-6 levels may improve the prediction of atherosclerosis development in these patients." (PMID 39766337, 2024). "Higher concentrations of IL-6 also have been observed in atherosclerosis patients." (PMID 36672997, 2023). "Recent research has identified IL-6 antagonists, such as tocilizumab and ziltivekimab, as potential therapeutic options to improve endothelial function, which can be used as preventive medication for atherosclerosis." (PMID 37659996, 2023). "Several studies have demonstrated that ApoA1 exerts regulatory effects on cholesterol levels, IL-2 receptor expression, and IL-6 expression in Treg cells during the progression of atherosclerosis, thereby impeding the transition from exTregs to Tfh cells and ultimately reducing atherosclerosis." (PMID 38143759, 2023). "IL-6, a member of the IL family, plays a proinflammatory role inducing the adhesion and aggregation of inflammatory cells throughout the organism which explains its involvement in the development of atherosclerosis and thrombosis." (PMID 38017432, 2023). "We hypothesize that IL-6, a pleiotropic pro-inflammatory cytokine playing key roles in atherosclerosis, may significantly contribute to BBB dysfunction, too." (PMID 36882782, 2023).
atherosclerosis (continued). "Former data have documented that IL-6 is not only a significant contributor to the early onset of atherosclerosis but is also a marker of the greater extent of atherosclerotic lesions, involving other pro-inflammatory cytokines, like IL-1 and tumor necrosis factor alpha (TNF-α), as well." (PMID 36835838, 2023). "IL-6 hasbeen identified as a potential trigger for the pathophysiology of atherosclerosis." (PMID 39076704, 2023). "This study also identified a positive feedback loop between mitochondrial dysfunction and increased IL-6 levels within the aorta during aging, which could accelerate atherosclerosis." (PMID 37759225, 2023). "Microglia cells express receptors for various cytokines produced by cellular components of the BBB during atherosclerosis, including IL-6, which may contribute to microglia activation." (PMID 36882782, 2023). "In addition, interleukin-6 (IL-6), whose levels are increased in IBD, is linked to endothelial dysfunction, early atherosclerosis, and coronary heart disease." (PMID 37260950, 2023). "Additionally, new biomarkers of atherosclerosis (IL-6, MPO, TNF-alpha) will be measured every 6 months." (PMID 37590267, 2023). "Overall, these results suggested that aberrant DNA demethylation modifications (ie. p66Shc, Drp1, Ribonuclease 6, IL-6, SLAM7, and lipoprotein-associated phospholipase A2) contribute to atherosclerosis progression and its potential role in atherosclerosis as a therapeutic target." (PMID 38031118, 2023). "Chemotactic factor (Mcp-1) and inflammatory cytokines (Tnf-α, Il-1β, and Il-6) are released during the initial stage of atherosclerosis, where they trigger the infiltration of monocytes across the endothelium and promote the formation of atherosclerotic plaques." (PMID 37836404, 2023). "Therefore, our article aims to focus on presenting the latest evidence that supports the significance of two particular molecules, interleukin 6 (IL-6) and apolipoprotein B (apoB), as potential biomarkers for atherosclerosis." (PMID 37629496, 2023). "IL-6 signaling may promote experimental atherosclerosis and modulate healing of the infarcted myocardium, but consensus regarding these effects is lacking." (PMID 37259918, 2023). "Likewise, while elevation of IL-6 is closely related to atherosclerosis, myocardial infarction, and heart failure, its transient increase also plays a role in tissue proliferation." (PMID 37880253, 2023). "IL-6 plays a key role as an upstream cytokine in the propagation of the inflammatory response downstream of atherosclerosis, and the high production of IL-6 stimulates hepatocytes to generate C-reactive protein (CRP), which further amplifies the inflammatory response." (PMID 37485268, 2023). "Of particular note, toxic metals such as mercury, lead, and cadmium may contribute to the development of MetS by altering oxidative stress, IL-6 signaling, apoptosis, altered lipoprotein metabolism, fluid shear stress and atherosclerosis, and other mechanisms." (PMID 37624175, 2023). "Streptococcus is known for mediating immune response via proinflammatory cytokines (interleukin-1 and interleukin-6), whereas Peptostreptococcaceae is involved in atherosclerosis and might promote the growth of aneurysms." (PMID 37928732, 2023). "Because it was reported that adenine might suppress inflammatory cytokines secretion and, thus, explain a reduction in atherosclerosis, we tested plasma levels of interleukin 6 (IL-6) and tumor necrosis factor alpha (TNFα)." (PMID 36844738, 2023). "Temporary hypocortisolism may lead to subsequent increase of inflammatory markers being involved in atherosclerosis such as Interleukin 1 (IL-1), Interleukin 6 (IL-6), and tumor-necrosis factor (TNF)." (PMID 37008924, 2023).